PPIAL4F (peptidylprolyl isomerase A like 4F)
Description:
PPIases accelerate the folding of proteins. It catalyzes the cis-trans isomerization of proline imidic peptide bonds in oligopeptides (By similarity).
Tractability: No criterion of Open Targets' tractability assessment is met for any kind of drug.
Gene: Protein-coding gene on chromosome 1 (144,592,893 to 144,593,652, forward strand). Ensembl gene ENSG00000279782.
Subcellular location: Cytoplasm
Gene Ontology:
Molecular function: cyclosporin A binding; peptidyl-prolyl cis-trans isomerase activity
Biological process: protein folding
Cellular component: cytoplasm
Homologues: Orthologues: zebrafish ppifa (68% identical), zebrafish ppiab (68% identical), Caenorhabditis elegans cyn-3 (65% identical), Caenorhabditis elegans cyn-7 (65% identical), zebrafish ppiaa (64% identical), Caenorhabditis elegans cyn-2 (63% identical), Caenorhabditis elegans cyn-1 (60% identical), Caenorhabditis elegans cyn-9 (49% identical), Drosophila melanogaster Cyp40 (49% identical), Drosophila melanogaster Moca-cyp (46% identical). Paralogues in human: PPIAL4E (100% identical), PPIAL4D (99% identical), PPIAL4C (98% identical), PPIAL4A (98% identical), PPIAL4G (96% identical), PPIAL4H (96% identical), PPIA (85% identical), PPIF (66% identical), PPIE (61% identical), PPID (60% identical), PPIB (56% identical), PPIC (53% identical), and 10 more.